GTPBP3 (GTP binding protein 3, mitochondrial)
Description:
GTPase component of the GTPBP3-MTO1 complex that catalyzes the 5-taurinomethyluridine (taum(5)U) modification at the 34th wobble position (U34) of mitochondrial tRNAs (mt-tRNAs), which plays a role in mt-tRNA decoding and mitochondrial translation. Taum(5)U formation on mammalian mt-tRNA requires the presence of both GTPBP3-mediated GTPase activity and MTO1 catalytic activity.
Synonyms: MTGP1; MSS1; THDF1; GTPBG3; FLJ14700; COXPD23
Tractability: PROTAC: ubiquitination databases record sites on it; its protein half-life has been measured.
Gene: Protein-coding gene on chromosome 19 (17,334,920 to 17,342,735, forward strand). Ensembl gene ENSG00000130299.
Subcellular location: Mitochondrion; Cytoplasm (Isoform 4)
Subcellular location (Human Protein Atlas): Mitochondria
Pathways (Reactome):
Metabolism of RNA: tRNA modification in the mitochondrion
Gene Ontology:
Molecular function: GTPase activity; protein binding; tRNA 5-taurinomethyluridine synthase activity; GTP binding
Biological process: mitochondrial tRNA wobble uridine modification; tRNA methylation; tRNA wobble uridine modification; mitochondrial tRNA modification; tRNA modification
Cellular component: cytoplasm; GTPBP3-MTO1 complex; mitochondrion
Genetic constraint (gnomAD): Loss-of-function variants: 35 observed, 41.72 expected, observed/expected ratio (o/e) 0.84, 90% interval 0.64 to 1.11. The upper end of that interval is the gene's LOEUF score, 1.11, which puts it in group 4 of 6, group 1 being the genes least tolerant of losing a copy. Missense variants: 691 observed, 682.74 expected, observed/expected ratio (o/e) 1.01, 90% interval 0.95 to 1.08. Synonymous variants: 332 observed, 314.42 expected, observed/expected ratio (o/e) 1.06, 90% interval 0.96 to 1.16.
Gene-disease validity (ClinGen):
ClinGen rates the evidence that GTPBP3 causes each of these diseases.
mitochondrial disease (autosomal recessive): Definitive.
Leigh syndrome (autosomal recessive): Moderate. A progressive neurological disease defined by specific neuropathological features associating brainstem and basal ganglia lesions.
Homologues: Orthologues: chimpanzee GTPBP3 (99% identical), macaque GTPBP3 (97% identical), dog GTPBP3 (87% identical), pig GTPBP3 (86% identical), mouse Gtpbp3 (81% identical), rat Gtpbp3 (80% identical), guinea pig GTPBP3 (80% identical), zebrafish gtpbp3 (56% identical), tropical clawed frog gtpbp3 (56% identical), Drosophila melanogaster CG18528 (45% identical), Caenorhabditis elegans mtcu-1 (32% identical). Paralogues in human: ERAL1 (16% identical).
Diseases named in the same sentence as GTPBP3 in open-access papers:
GTPBP3 is named in the same sentence as 31 diseases in open-access papers, as found by Europe PMC text mining. Sharing a sentence is not in itself a finding about the gene and the disease. The quoted sentences say what the papers report.
hypertrophic cardiomyopathy (10 papers, 2015 to 2025). A condition in which the myocardium is hypertrophied without an obvious cause. "Knockout of Gtpbp3 in zebrafish caused hypertrophic cardiomyopathy and showed abnormal mitochondrial tRNA metabolism." (PMID 36551964, 2022). "Mutations in GTPBP3 cause mitochondrial translation defects that are associated with hypertrophic cardiomyopathy." (PMID 36274122, 2022). "In particular, GTPBP3 deficiency was associated with hypertrophic cardiomyopathy, lactic acidosis, and encephalopathy." (PMID 30916346, 2019). "We then investigated if the gtpbp3ko zebrafish recapitulated the hypertrophic cardiomyopathy phenotypes in patients carrying the GTPBP3 mutations." (PMID 30916346, 2019). "The previous investigations showed that GTPBP3 mutations were associated with hypertrophic cardiomyopathy (HCM)." (PMID 30916346, 2019). "Like MTO1 mutations, GTPBP3 mutations (MIM 608536) are mostly associated with hypertrophic cardiomyopathy, lactic acidosis, and combined respiratory chain deficiency." (PMID 26642043, 2015). "Our study suggests that despite deficiencies in either MTO1 or GTPBP3 cause hypertrophic cardiomyopathy with lactic acidosis, the underlying metabolic signalling in patient cells may be different (see Supplementary Discussion)." (PMID 29348686, 2018). "In humans, GTPBP3 mutations cause hypertrophic cardiomyopathy with lactic acidosis, and have been associated with a defect in mitochondrial translation, yet the pathomechanism remains unclear." (PMID 26642043, 2015). "Mutations in GTPBP3 cause hypertrophic cardiomyopathy, lactic acidosis and encephalopathy, and they have been associated with a defect in mitochondrial translation, although the pathomechanism remains unclear." (PMID 26642043, 2015). "However, the specific pathogenic mechanism of mitochondrial dysfunction caused by GTPBP3 defect leading to hypertrophic cardiomyopathy remains unclear." (PMID 36980825, 2023). "Furthermore, the defective τm5U34 modification and mitochondrial translations were observed in mutant cell lines carrying the GTPBP3 mutations, derived from patients of families with hypertrophic cardiomyopathy (HCM) characterized by myocardial and myocyte hypertrophy in left ventricle." (PMID 30916346, 2019). "In brief, we present here C. elegans models for the human diseases associated with hypomodification at position 2 and 5 of U34 in a mt-tRNA set, which exhibit different phenotypes: liver failure (TRMU) or hypertrophic cardiomyopathy (GTPBP3 and MTO1)." (PMID 28732077, 2017). "MTO1 mutations cause combined oxidative phosphorylation deficiency 10 (COXPD10), presenting with infantile hypertrophic cardiomyopathy and lactic acidosis, while GTPBP3 mutations cause COXPD23, characterized by early childhood hypertrophic cardiomyopathy and neurological symptoms." (PMID 41465450, 2025). "More recently, patients exhibiting hypertrophic cardiomyopathy and lactic acidosis as a consequence of a combined respiratory chain deficiency have been found to carry mutations in MTO1 and GTPBP3." (PMID 25806043, 2015). "Notably, in addition to hypertrophic cardiomyopathy, lactic acidosis, and combined OXPHOS deficiency, some patients with GTPBP3 mutations also developed encephalopathy." (PMID 25806043, 2015). "They include MELAS (mitochondrial encephalomyopathy and lactic acidosis with stroke-like episodes), MERRF (myoclonic epilepsy and ragged-red fiber), TRMU-dependent acute infantile liver failure and hypertrophic cardiomyopathies dependent on MTO1 and GTPBP3." (PMID 26642043, 2015).
lactic acidosis (9 papers, 2015 to 2025). Metabolic acidosis characterized by the accumulation of lactate in the body. "Depletion of GTPBP3 leads to respiratory defects, impaired mitochondrial translation, and lactic acidosis." (PMID 41377071, 2025). "In both cases, the uncoupling is expected to result in lactic acidosis, a common clinical trait present in MTO1 and GTPBP3 patients." (PMID 29348686, 2018).
developmental delay (2 papers, 2021 to 2023). "However, the patient’s clinical manifestations (developmental delay, fatigability, and hyperlactacidemia) are highly consistent with COXPD23 caused by GTPBP3 defects." (PMID 34276756, 2021).
glaucoma (2 papers, 2022). Increased pressure in the eyeball due to obstruction of the outflow of aqueous humor. "Moreover, GTPBP3 is also correlated with primary angle closure glaucoma and non-syndromic hearing loss." (PMID 35985767, 2022). "The results of whole exome sequencing suggested that GTPBP3 might be related to the development of glaucoma." (PMID 36056163, 2022).
deafness (1 paper, 2010). An inherited or acquired condition characterized by the complete loss of the ability to hear from one or both ears. "Using this method, the DFNM1 locus, a modifier of DFNB26-linked deafness was identified and the deafness phenotype associated with the 1555A>G mutation in MTRNR1 was shown to be modified by three different genes: MTO1, TFB1M and GTPBP3." (PMID 21119891, 2010).
glioma (1 paper, 2024). A benign or malignant brain and spinal cord tumor that arises from glial cells (astrocytes, oligodendrocytes, ependymal cells). "The expression of HAVCR2, PVR, TNFRSF25, and TNFSF15 showed a positive correlation with the expression of numerous MRM-related genes like GTPBP3, METTL2A, METTL6, METTL8, NSUN4, and TRMT61A in glioma cells." (PMID 38824202, 2024). "We observed the high expression levels of METLL8, METLL2A, TRMT112, METTL2B, GTPBP3, METTL6, and NSUN4 in cells in the S, G2M, and G1 phases, which were similar for astrocytes, glioma cells, and oligodendrocytes." (PMID 38824202, 2024). "In glioma cells, it was observed that the expression of genes related to MRM, like GTPBP3, METTL2A, METTL6, METTL8, NSUN4, and TRMT61A, showed positive correlation with the expression of HAVCR2, PVR, TNFRSF25 and TNFSF15 as revealed by scRNA-seq analysis." (PMID 38824202, 2024).
heart failure (1 paper, 2017). Inability of the heart to pump blood at an adequate rate to meet tissue metabolic requirements. "Mutations in MTO1 or GTPBP3 impair the modification of the wobble uridine at position 5 of the pyrimidine ring and cause heart failure." (PMID 28732077, 2017). "Presently, however, it is very unclear how TRMU mutations lead to liver disease while those in GTPBP3 and MTO1 lead to heart failure." (PMID 28732077, 2017).
mitochondrial disease (6 papers, 2019 to 2025). "This study highlights the important role of mt-tRNA modification defects in mitochondrial diseases and provides a reference for the diagnosis of diseases related to GTPBP3 deficiency, as well as subsequent prenatal diagnosis and genetic counseling." (PMID 39719609, 2024). "GTPBP3 is a catalytic enzyme involved in the synthesis of τm5(s2) U in mitochondria and has been associated with mitochondrial diseases." (PMID 39719609, 2024). "Combined Oxidative Phosphorylation Deficiency 23 (COXPD23) caused by mutations in GTPBP3 gene is a rare mitochondrial disease, and this disorder identified from the Chinese population has not been described thus far." (PMID 34276756, 2021). "The association between GTPBP3 mutations and mitochondrial disease was first described in 2014." (PMID 34276756, 2021). "Loss of taurine modifications caused by mutations in MTO1, GTPBP3, mt-tRNALeu(UUR), or mt-tRNALys genes causes various mitochondrial diseases, which will be described in a later section." (PMID 39719325, 2025). "GTPBP3 catalyzes τm5(s2) U biosynthesis at the 34th wobble position of mitochondrial tRNAs, the hypomodification of τm5U leads to mitochondrial disease." (PMID 39719609, 2024).
GTPBP3 also shares sentences with these, for which no sentence is quoted: Encephalopathy (3 papers); breast carcinoma (2); infantile hypertrophic cardiomyopathy (2); MELAS (2); primary angle-closure glaucoma (2); Arrhythmia (1); brain disorder (1); brain malformations (1); cancer (1); cardiomyopathy (1); congestive heart failure (1); Crohn disease (1); hereditary cardiomyopathy (1); Hypoglycemia (1); infection (1); Intellectual disability (1); liver failure (1); metabolic acidosis (1); Mitochondrial myopathy (1); myocardial hypertrophy (1); OXPHOS disease (1); Stroke (1); tumor (1).